ZNF19 (zinc finger protein 19)
Description:
May be involved in transcriptional regulation.
Synonyms: KOX12; MGC51021
Tractability: PROTAC: ubiquitination databases record sites on it.
Gene: Protein-coding gene on chromosome 16 (71,464,555 to 71,565,502, reverse strand). Ensembl gene ENSG00000157429.
Subcellular location: Nucleus
Subcellular location (Human Protein Atlas): Mitochondria
Pathways (Reactome):
Gene expression (Transcription): Generic Transcription Pathway
Gene Ontology:
Molecular function: protein binding; DNA-binding transcription factor activity, RNA polymerase II-specific; RNA polymerase II transcription regulatory region sequence-specific DNA binding; sequence-specific double-stranded DNA binding
Biological process: regulation of transcription by RNA polymerase II; regulation of DNA-templated transcription
Cellular component: nucleus
Genetic constraint (gnomAD): Loss-of-function variants: 9 observed, 11.21 expected, observed/expected ratio (o/e) 0.8, 90% interval 0.48 to 1.4. The upper end of that interval is the gene's LOEUF score, 1.4, which puts it in group 5 of 6, group 1 being the genes least tolerant of losing a copy. Missense variants: 341 observed, 362.83 expected, observed/expected ratio (o/e) 0.94, 90% interval 0.86 to 1.03. Synonymous variants: 111 observed, 124.92 expected, observed/expected ratio (o/e) 0.89, 90% interval 0.76 to 1.04.
Homologues: Orthologues: chimpanzee ZNF19 (99% identical), macaque ZNF19 (94% identical), dog ZNF19 (83% identical), Drosophila melanogaster CG3281 (28% identical), Drosophila melanogaster CG2712 (24% identical), Drosophila melanogaster Phs (21% identical). Paralogues in human: ZNF599 (45% identical), ZNF264 (44% identical), ZNF805 (44% identical), ZNF619 (42% identical), ZNF582 (41% identical), ZNF614 (41% identical), ZNF169 (41% identical), ZFP37 (40% identical), ZFP90 (40% identical), ZNF529 (40% identical), ZNF875 (40% identical), ZNF133 (40% identical), and 50 more.
Diseases named in the same sentence as ZNF19 in open-access papers:
ZNF19 is named in the same sentence as 2 diseases in open-access papers, as found by Europe PMC text mining. Sharing a sentence is not in itself a finding about the gene and the disease. The quoted sentences say what the papers report.
hepatoma (1 paper, 2025). "HCS assays indicated that inhibition of LARS2 and ZNF19 contributed to decreased tumor cell proliferation, suggesting a molecular mechanism behind melittin’s anti-hepatoma activity." (PMID 41157110, 2025).
ZNF19 also shares sentences with these, for which no sentence is quoted: tumor (2 papers).